ZNF408 (zinc finger protein 408)
Description:
May be involved in transcriptional regulation.
Synonyms: PRDM17; FLJ12827; EVR6; RP72
Tractability: No criterion of Open Targets' tractability assessment is met for any kind of drug.
Gene: Protein-coding gene on chromosome 11 (46,701,016 to 46,705,912, forward strand). Ensembl gene ENSG00000175213.
Subcellular location: Nucleus
Subcellular location (Human Protein Atlas): Centriolar satellite; Cytosol
Gene Ontology:
Molecular function: identical protein binding; protein binding; DNA-binding transcription factor activity, RNA polymerase II-specific; RNA polymerase II cis-regulatory region sequence-specific DNA binding
Biological process: regulation of transcription by RNA polymerase II
Cellular component: nucleus
Genetic constraint (gnomAD): Loss-of-function variants: 24 observed, 29.45 expected, observed/expected ratio (o/e) 0.82, 90% interval 0.59 to 1.15. The upper end of that interval is the gene's LOEUF score, 1.15, which puts it in group 5 of 6, group 1 being the genes least tolerant of losing a copy. Missense variants: 897 observed, 971.72 expected, observed/expected ratio (o/e) 0.92, 90% interval 0.87 to 0.98. Synonymous variants: 410 observed, 407.16 expected, observed/expected ratio (o/e) 1.01, 90% interval 0.93 to 1.09.
Homologues: Orthologues: chimpanzee ZNF408 (99% identical), macaque ZNF408 (94% identical), dog ZNF408 (83% identical), pig ZNF408 (80% identical), rabbit ZNF408 (78% identical), mouse Zfp408 (67% identical), tropical clawed frog znf408 (38% identical), zebrafish znf408 (38% identical). Paralogues in human: ZNF407 (20% identical), ZNF287 (19% identical), ZKSCAN7 (19% identical), ZBTB17 (18% identical), ZNF333 (18% identical), ZNF777 (18% identical), ZNF17 (18% identical), ZNF426 (18% identical), ZNF136 (17% identical), ZNF34 (17% identical), ZNF527 (17% identical), MYNN (17% identical), and 38 more.
Diseases named in the same sentence as ZNF408 in open-access papers:
ZNF408 is named in the same sentence as 5 diseases in open-access papers, as found by Europe PMC text mining. Sharing a sentence is not in itself a finding about the gene and the disease. The quoted sentences say what the papers report.
cancer (1 paper, 2021). A tumor composed of atypical neoplastic, often pleomorphic cells that invade other tissues. "On the other hand, CGI reported SRC as the only predicted cancer driver with an oncogenic function, whereas OGFOD2 and ZNF408 were annotated as passenger mutations." (PMID 33916261, 2021).
ZNF408 also shares sentences with these, for which no sentence is quoted: retinal disease (2 papers); exudative vitreoretinopathy (1); Familial exudative vitreoretinopathy (1); microcephaly-lymphedema-chorioretinal dysplasia (1).